VEGFA (vascular endothelial growth factor A)
Diseases named in the same sentence as VEGFA in open-access papers (continued):
Sharing a sentence is not in itself a finding about the gene and the disease.
epilepsy (25 papers, 2012 to 2025). A brain disorder characterized by episodes of abnormally increased neuronal discharge resulting in transient episodes of sensory or motor neurological dysfunction, or psychic dysfunction. "We observed that VEGFA promotes increased risk in epilepsy, FE, and GE." (PMID 39315097, 2024). "However, VEGFA also have a dual role in epilepsy, as it has been linked to blood-brain barrier disruption and epileptogenic inflammation, contributing to the development of epilepsy." (PMID 40217519, 2024). "The expression levels of SQSTM1 and VEGFA in epilepsy model samples were significantly higher than those in normal control, while BNIP and WIPI2 expression levels were notably decreased." (PMID 40217519, 2024). "The results indicated that SQSTM1 and VEGFA exhibited significantly higher expression levels in epilepsy rats compared to the control group." (PMID 40217519, 2024). "CXCL11 levels and VEGFA levels increased the risk of epilepsy, CXCL1 levels, CXCL9 levels, IL-6 levels, TRAIL levels, and VEGFA levels were associated with an increased risk of FE and TTNFSF14 levels, VEGFA levels were associated with an increased risk of GE." (PMID 39315097, 2024). "Two inflammatory proteins, namely, C-X-C motif chemokine 11(CXCL11) levels (OR=1.1078, 95%CI =1.0255~ 1.1967, P=0.0093) and Vascular endothelial growth factor A (VEGFA) levels (OR=1.0721, 95%CI =1.0219~ 1.1247, P=0.0044) were positively associated with epilepsy." (PMID 39315097, 2024). "We did not observe differential RNA or protein expression of HIF-1α and its target VEGFA between the epileptogenic GBMs and tumors that did not cause epilepsy." (PMID 30621209, 2019). "We found that SQSTM1 and VEGFA were significantly upregulated, while BNIP and WIPI2 were significantly downregulated in epilepsy model." (PMID 40217519, 2024). "We performed qPCR experiments and immunohistochemistry on tissue microarrays containing 286 GBMs to further explore the association of these candidate pathways and of markers of mesenchymal transformation (NF-κB, CEBP-β, STAT3, STAT5b, VEGFA, SRF) with epilepsy." (PMID 30621209, 2019).
invasive breast carcinoma (25 papers, 1999 to 2024). A carcinoma that infiltrates the breast parenchyma. "Expression of miR-20a in breast invasive carcinomas is associated with a distinctive angiogenic pattern consisting in large vessels, anomalous glomeruloid microvascular proliferations and high VEGFA expression." (PMID 29617404, 2018). "In invasive breast carcinomas, TAMs have been shown to express a significant level of VEGFA mRNA and protein, suggesting a role for macrophages in tumor angiogenesis." (PMID 32318345, 2020).
pancreatic neuroendocrine tumor (25 papers, 2005 to 2024). Pancreatic endocrine tumor, also known as pancreatic neuroendocrine tumor (PNET), describes a group of endocrine tumors originating in the pancreas that are usually indolent and benign, but may have the potential to be malignant. "Accordingly, vague resistance to anti-angiogenic therapy by VEGFA signaling blockade was found to be responsible for the upregulation of Ang-2 in late stage pancreatic neuroendocrine tumors." (PMID 36556457, 2022).
rosacea (25 papers, 2015 to 2026). A chronic erythematous skin disorder that affects the face. "Pro-angiogenic factors, such as VEGFA, are upregulated in rosacea lesions and promote neovascularization and vasodilation, worsening the clinical erythema." (PMID 40725084, 2025). "Related studies have also reported increased VEGFA levels as well as enhanced angiogenesis in lesional skin of rosacea." (PMID 34993194, 2021). "Our study showed that vasoactive molecule VEGFA mRNA expression was enhanced in rosacea patients." (PMID 34993194, 2021). "An anti-malarial drug, Artemisinin, decreased the expression of Angiopoietin 2 and VEGFC, but not VEGFA or VEGFB, in a mouse model of rosacea induced by LL37, the proinflammatory form of cathelicidin, and showed a beneficial clinical effect in rosacea patients." (PMID 41562711, 2025). "VEGFA, rather than VEGFB was highly expressed in rosacea lesions." (PMID 34993194, 2021).
sarcoidosis (25 papers, 2006 to 2025). Sarcoidosis is a multisystemic disorder of unknown cause characterized by the formation of immune granulomas in involved organs. "Among the identified miRNAs involved in sarcoidosis, hsa-miR-126 was highly expressed, and the two target genes VEGFA and NR3C1 were also highly expressed in lymph node samples of sarcoidosis." (PMID 34055877, 2021). "In sarcoidosis pathological tissue, hsa-miR-126 was highly expressed, and VEGFA and NR3C1 were overexpressed." (PMID 34055877, 2021). "Further research evaluated the VEGFA level in serum, as well as bronchoalveolar lavage (BAL) and found similar results: VEGFA was remarkably higher in individuals with sarcoidosis relative to the healthy controls (p = 0.0002)." (PMID 34055877, 2021). "From our results, we found that VEGFA and NR3C1 were overexpressed in the pathological tissue of sarcoidosis, which was mainly regulated by hsa-miR-126." (PMID 34055877, 2021).
neuroendocrine tumors (24 papers, 2010 to 2025). "Well-differentiated neuroendocrine tumors (NETs) are highly vascularized neoplasms characterized by expression of vascular endothelial growth factor-A (VEGF-A)." (PMID 39834129, 2025). "Neuroendocrine neoplasms are densely vascularized and express hypoxia-inducible factor (HIF)-1α and vascular endothelial growth factor A (VEGF-A)." (PMID 32156252, 2020).
neutropenia (24 papers, 2007 to 2025). A decrease in the number of neutrophils found in the blood. "Previous studies had also confirmed that Bevacizumab, a monoclonal antibody targeting vascular endothelial growth factor A, had efficacy in improving pathological complete response (pCR) rates when added into the neoadjuvant chemotherapy for TNBCs, with increased risk of neutropenia." (PMID 35875141, 2022).
Retinal hemorrhage (24 papers, 2010 to 2026). Bleeding located within the retina. "Based on the involvement of VEGFA in DR, it was intriguing to hypothesize that miR-1281 could be related to the microangiopathic damage of retinal vessels by up-regulating the expression of VEGFA, whose intimate role in retinal neovascularization and retinal hemorrhage is well-established." (PMID 32849308, 2020).
colon adenocarcinoma (23 papers, 2002 to 2024). "The expression levels of CXC chemokines and VEGFA have been studied in a range of tumor types; however, findings are contradictory with regard to colonic adenocarcinomas." (PMID 36246978, 2022). "The amount of VEGFA in the cell is tightly regulated: A two-fold increase of VEGFA is embryonically lethal, and reduced expression is found in high-grade colon adenocarcinomas." (PMID 27490485, 2016). "We next investigated whether changes in TBP expression could alter VEGFA expression in a transformed cell line using HT-29 human colon adenocarcinoma cells." (PMID 28415573, 2017). "We next examined whether there was any correlation between TGF-beta signaling and VEGFA expression in human colonic adenocarcinomas." (PMID 23536895, 2013). "Exploring the expression level, gene regulatory network, prognostic value, and target prediction of the CXC chemokine-VEGFA network in colon adenocarcinoma (COAD) is crucial from the perspective of tumor angiogenesis." (PMID 36246978, 2022). "Overall, normal colonic epithelial cells display higher nuclear Smad2 phosphorylation and lower VEGFA expression than adenocarcinomas, supporting the view that expression of VEGFA inversely correlates with TGF-beta signaling in human colonic adenocarcinoma." (PMID 23536895, 2013).
Ewing sarcoma (23 papers, 2010 to 2025). A small round cell tumor that lacks morphologic, immunohistochemical, and electron microscopic evidence of neuroectodermal differentiation. "Inhibition of VEGFA expression in human Ewing sarcoma cells can inhibit cell growth and tubule formation." (PMID 38240704, 2024). "In particular, Ewing sarcoma cells produce several VEGF isoforms including soluble spliced isoform of VEGFA, VEGF-165, which promotes the recruitment of bone marrow derived cells." (PMID 31370265, 2019). "Our analyses show that Ewing sarcoma tumor cells express VEGFA." (PMID 37823774, 2023). "Our work demonstrated that it reduces in a dose- and in a time-dependent manner the expression of Gli1, NR0B1, FOXM1 and VEGFA, some of the EWS-Fli1 target-genes considered as determining factors in the carcinogenesis of Ewing Sarcoma." (PMID 27006472, 2016).
gastric ulcer (23 papers, 2009 to 2024). An ulcerated lesion in the mucosal surface of the stomach. "The number of microvessels and CD31 expression were lower in TPKO than in WT mice, and TPKO suppressed the expression of transforming growth factor beta (TGF‐β) and vascular endothelial growth factor A (VEGF‐A) in areas around gastric ulcers." (PMID 34655121, 2022).
intrauterine growth restriction (23 papers, 2010 to 2026). "In addition, the protein expression of leptin, VEGFA, IL-6 was increased and negatively correlated to mTORC2 signaling in human placentas collected from pregnancies complicated by intrauterine growth restriction (IUGR)." (PMID 34805133, 2021).
Retinal atrophy (23 papers, 2016 to 2025). A nonspecific term denoting wasting, especially as a result of degeneration, of the retinal pigment epithelium (RPE) and neurosensory retinal cells. "The results showed that, in the retinas of SNX31m/m mice, VEGFA was significantly upregulated when vascular leakage began to appear at 2 months of age but decreased significantly at 4 months of age during the retinal atrophy period." (PMID 37053012, 2023). "The findings of this study can relate the acute LD model to fundamental aspects of patients suffering from neovascular AMD: neurodegeneration and impairment of retinal function, VEGFA up-regulation, neovascularization in the photoreceptor layer and in the end retinal atrophy." (PMID 32286488, 2020).
adenomyosis (22 papers, 2012 to 2026). The growth of endometrial tissue inside the muscular wall of the uterine corpus. "Therefore, STAT3, VIM, VEGFA and HSP90B1 that were also annotated in interleukin-4 and interleukin-13 signalling in the present GSEA need to be validated to verify potential downregulation of this pathway in women with adenomyosis." (PMID 32933042, 2020).
chronic myeloid leukemia (22 papers, 2011 to 2025). "Its enhancer is active in embryogenesis and then switched off by methylation, but in chronic myeloid leukemia, it is hypomethylated and, consequently, VEGFA overexpressed." (PMID 35454885, 2022). "The vascular endothelial growth factor A (VEGFA) enhancer, located 157 Kb downstream of its promoter, is demethylated in chronic myeloid leukemia (CML)." (PMID 34316716, 2021). "In chronic myeloid leukemia (CML), the enhancer is demethylated and VEGFA is overexpressed." (PMID 34316716, 2021).
infantile hemangioma (22 papers, 2014 to 2025). "CircAP2A2 adsorbs miR-382-5p and regulates VEGFA expression to participate in the progression of infantile hemangioma." (PMID 40426921, 2025). "VEGFA plays an important role in vascular development and in pathological angiogenesis and its protein is highly expressed in vessels of proliferating infantile hemangioma." (PMID 26772808, 2016). "Interestingly, some of these genes also play roles in cell signaling pathways that have been linked to the pathogenesis of infantile hemangioma; namely, VEGFA in the VEGF/VEGFR pathway, ANGPT2 and ANGPTL1 in the Tie2/Angiopoietin signaling pathway and NOTCH3, NOTCH4 and JAG1 in the Notch pathway." (PMID 26772808, 2016).
brain cancer (21 papers, 2007 to 2025). A primary or metastatic malignant neoplasm affecting the brain. "For instance, VEGFA, HK2, and LDHA are linked to the HIF-1 signaling pathway and glycolysis/gluconeogenesis, underscoring their roles in the metabolic adaptations of the metastatic brain cancer cells." (PMID 40038276, 2025).
migraine (21 papers, 2016 to 2025). "We also identified pleiotropy at the SNPs level between the blood levels of VEGFA and migraine risk." (PMID 35546551, 2022). "Likewise, we identified a genome-wide pleiotropy between higher levels of VEGFA and migraine risk." (PMID 35546551, 2022). "Higher levels of VEGFA have also been found in migraine patients together with elevated CGRP and nitric oxide (NO)." (PMID 39044165, 2024). "Our findings of higher levels of MMP7 and VEGFA suggest enhanced permeability of BBB in all migraine patients." (PMID 35546551, 2022). "Among the identified 36 blood proteins with pleiotropic effects on migraine at SNPs within LD-independent loci, five proteins have two or more pleiotropic SNPs with migraine, including four SNPs for ERBB3, three SNPs for F2R, and two SNPs for B3GNT2, VEGFA and SCARF2." (PMID 35546551, 2022).
pneumonia (21 papers, 2010 to 2025). An acute, acute and chronic, or chronic inflammation focally or diffusely affecting the lung parenchyma, caused by an infection in one or both of the lungs (by bacteria, viruses, fungi, or mycoplasma.). "High VEGFA levels have been found in subjects with chronic pulmonary diseases and certain kinds of pneumonia, and have been found to be significantly higher in the serum of children with Mycoplasma pneumoniae infection and wheezing than in healthy controls." (PMID 25326706, 2014).
angina (20 papers, 2012 to 2025). "In addition, several clinical studies have also confirmed the beneficial effects of the local application of VEGFA, which has been shown to improve myocardial perfusion and function with sustained symptomatic relief in end‐stage angina pectoris." (PMID 40008489, 2025).
cerebrovascular diseases (20 papers, 2015 to 2025). "There are many factors affecting cardiovascular and cerebrovascular diseases, such as vascular endothelial growth factor A (VEGF-A), a dimer glycoprotein encoded by VEGF-A gene, which plays a crucial role in the process of inducing vascular growth." (PMID 38994338, 2024). "Further exploration into using VEGFA isoforms is one way to improve VEGFA pro-angiogenic therapy to treat cerebrovascular diseases." (PMID 37189449, 2023). "VEGFA pro-angiogenic therapy can be further improved for treatment of cerebrovascular diseases by increasing dosage, targeted administration to the afflicted area, and consideration of the timing of administration." (PMID 37189449, 2023). "Nonetheless, 165 is one of the few VEGFA isoforms to be used as a treatment for cerebrovascular disease." (PMID 37189449, 2023). "Differences in receptor interaction gives each VEGFA isoform unique and varying biological effects that can be manipulated and optimized for treatment of cerebrovascular diseases." (PMID 37189449, 2023). "Further studies to characterize the biological effects of this isoform are necessary, as 145 is a strong candidate for a pro-angiogenic therapeutic for cerebrovascular diseases that avoids the detriments seen with VEGFA." (PMID 37189449, 2023). "VEGFA therapy is ideal for treating cerebrovascular diseases, where the main issue is vascular dysfunction or injury." (PMID 37189449, 2023). "While there have been trials addressing VEGFA treatment for cerebrovascular diseases, a majority of clinical trials using VEGFA pro-angiogenic therapy have been conducted in coronary artery related dysfunctions." (PMID 37189449, 2023). "If VEGFA induced angiogenesis can be used to grow new functioning blood vessels to replace the dysfunctional ones, patients suffering from cerebrovascular disease can be treated and patient outcome improved." (PMID 37189449, 2023). "Since the administration of perlecan with 189 resulted in therapeutic results, other combination-based therapeutics with VEGFA or their isoforms may also prove beneficial for cerebrovascular diseases." (PMID 37189449, 2023). "The varying effects produced by the VEGFA isoforms may be the key in furthering the utility of VEGFA pro-angiogenic therapy for cerebrovascular diseases." (PMID 37189449, 2023). "Because of the different biological effects elicited, VEGFA isoforms may hold promise as a tangible potential therapeutic for cerebrovascular diseases." (PMID 37189449, 2023). "In cerebrovascular disease, VEGFA can have both beneficial and detrimental effects." (PMID 37189449, 2023). "VEGFA is able to produce several different isoforms through alternative splicing, each of which has its own biological effect and may hold promise as a tangible potential therapeutic for cerebrovascular diseases." (PMID 37189449, 2023).
diabetic cardiomyopathy (20 papers, 2013 to 2025). Diabetic cardiomyopathy is a disorder of the heart muscle in people with diabetes. "Melatonin treatment may also prevent the development of diabetic cardiomyopathy through increasing the phosphorylation of vascular endothelial growth factor-A (VEGF-A) resulting in the inhibition of cardiac enlargement and hypertrophy in STZ-induced diabetic rats." (PMID 32280378, 2020).